THBS1-IT1 (THBS1 intronic transcript 1)
Synonyms: TBULC
Gene: Long non-coding RNA gene on chromosome 15 (39,586,561 to 39,587,293, forward strand). Ensembl gene ENSG00000276107.
Diseases named in the same sentence as THBS1-IT1 in open-access papers:
THBS1-IT1 is named in the same sentence as 4 diseases in open-access papers, as found by Europe PMC text mining. Sharing a sentence is not in itself a finding about the gene and the disease.
THBS1-IT1 shares sentences with these, for which no sentence is quoted: infection (1 paper); lung adenocarcinoma (1); lung squamous cell carcinoma (1); tumor (1).